CCL22 (C-C motif chemokine ligand 22)
Diseases named in the same sentence as CCL22 in open-access papers (continued):
Sharing a sentence is not in itself a finding about the gene and the disease.
cervical carcinoma (continued). "Therefore, CCL22 is secreted by M2-like macrophages and cervical cancer cells in cervical cancer." (PMID 31842422, 2019). "Thus, CCL22 may be a novel prognostic marker and therapeutic target for the treatment of cervical cancer." (PMID 31842422, 2019). "Moreover, many studies proved that cervical cancer cells could induce monocytes into M2 macrophages which was consistent with the result in our study to some degree that CCL22 in monocytes could be induced by cervical cancer cells." (PMID 31842422, 2019). "Therefore, CCL22 could polarize TAMs of cervical cancer toward M2a macrophages." (PMID 35805111, 2022). "However, the mechanism of CCL22 to promote cervical cancer progression remains unclear." (PMID 35805111, 2022). "Studies have found that high expression of CCL22 in the tumor microenvironment is closely related to lymph node recurrence in TSCC and poor prognosis of cervical cancer." (PMID 35480305, 2022). "Furthermore, we verify that CCL22 could polarize TAMs of cervical cancer into M2a macrophages." (PMID 35805111, 2022). "Within a study of our group, we retrospectively analyzed the clinical significance of the expression of CCL22 and FOXP3 in 230 cervical cancer patients." (PMID 34833360, 2021). "poly(I:C)‐stimulated supernatant of cervical cancer cells promoted M1‐type cytokine IL‐1β and IL‐6 expression of THP‐1–derived macrophages, but inhibited the expression of M2‐type cytokine, IL‐10 and CCL22." (PMID 31943744, 2020). "This study retrospectively analyzed the clinical significance of the expression of CCL22 and FOXP3 in 230 cervical cancer patients." (PMID 31842422, 2019). "However, the function of CCL22 in cervical cancer remains unknown." (PMID 31842422, 2019). "Tissue microarray by immunohistochemistry was performed to test the number of CCL22+ and FOXP3+ cells in a retrospective cohort of 230 cervical cancer cases, including 187 cases of squamous carcinoma and 43 cases of adenocarcinoma." (PMID 31842422, 2019). "In this study, by performing RT-PCR, we found that CCL22 was secreted exclusively from TAMs but not cervical cancer cells." (PMID 35805111, 2022). "CCL22, the dominant CCR4 ligand for Treg recruitment in tumors, has been described in different solid tumors (breast and cervical cancers, glioblastoma, squamous cell carcinoma (SCC), CRC and PDAC), where its expression correlates with Treg infiltrate and poor prognosis." (PMID 33924428, 2021). "Therefore, the CCL22+ infiltrating cells or the combination of CCL22 (+) and FOXP3 (+) cells are novel biomarkers that can be potentially used for cervical cancer prognosis." (PMID 31842422, 2019). "In cervical cancer, however, the correlation between protein expression levels of CCL22 and FOXP3, and the cell source of CCL22 have not been determined." (PMID 31842422, 2019). "Our study revealed a correlation between the expression of CCL22 and FOXP3 in cervical cancer." (PMID 31842422, 2019). "We found that CCL22 was mainly secreted by TAMs but not cervical cancer cell lines." (PMID 35805111, 2022). "Our study has demonstrated that CCL22 was secreted from TAMs but not cervical cancer cell lines." (PMID 35805111, 2022). "However, the expression of CCL22 in cervical cancer cells seems not to affect the survival rate of CC patients." (PMID 31842422, 2019). "The prognostic value of CCL22 in cervical cancer has, however, not been investigated." (PMID 31842422, 2019). "However, the prognostic role in cervical cancer for CCL22 was not clarified until recently." (PMID 34833360, 2021). "However, CCL22 expression in cervical cancer has not been previously determined." (PMID 31842422, 2019). "However, the prognostic role of CCL22 in cervical cancer (CC) has not been determined." (PMID 31842422, 2019). "In summary, these results showed that the level pattern of mRNA of FoxP3, CCL22/CCR4, OX40L/OX40 and Smad3 in cervical cancer immune microenvironment distinctly differed from that in normal cervix." (PMID 28086903, 2017).
cervical carcinoma (continued). "The FoxP3, CCL22 and CCR4 mRNA level in local immune microenvironment of normal cervix was lower than that in cervical cancer." (PMID 28086903, 2017).
lung carcinoma (12 papers, 2014 to 2024). "Importantly, given the common co-association of COPD and lung cancer, CCL22 has been implicated in tumorigenesis." (PMID 29042607, 2017). "Tumour cells, as well as tumour-associated macrophages and dendritic cells, produce high amounts of CCR4 ligands (CCL17 and CCL22) in breast, ovarian, and lung cancer patients." (PMID 38256152, 2024). "An inflammation score based on CXCL13 and three additional markers (CRP, MDC/CCL22, and IL-1RA) provided good separation in 10 year cumulative risks of lung cancer." (PMID 31354634, 2019). "Marked changes in gene expression were measured for Ccl2, Ccl7, Ccl17, Ccl22, Ccl3, Ccl4, Il-1α, Il-1ß, and Il-1rn (inflammation), Lpo and Noxo1 (oxidative stress), and Mmp12 (inflammation/lung cancer)." (PMID 29463257, 2018). "In the current study we investigated the association between CCL22 gene polymorphism at position 16C/A, and CCR4 gene polymorphism at position C1014T and lung cancer." (PMID 25031489, 2014). "Multi-SNP analysis and haplotype deduction is required to completely eliminate the role of CCL22 and CCR4 genetic changes in susceptibility to lung cancer." (PMID 25031489, 2014). "This further suggests that overexpression of CCL22 in osteoclasts may promote bone metastasis in certain types of lung cancer." (PMID 25031489, 2014). "Consistently, CCL22 producing osteoclasts and CCR4 expressing lung cancer cells were shown to be colocalized in bone metastases." (PMID 34064589, 2021). "USP17 could be induced by cytokines secreted from macrophages because various cytokines, including TNF-α, IL-1β, IL-4, IL-6, IL-8, IL-10, CXCL12, CCL18, and CCL22, were able to induce USP17 expression in H1299 and D121 lung cancer cells." (PMID 30038267, 2018). "The results of this study demonstrates that CCL22 gene polymorphism at position 16C/A and CCR4 gene polymorphism at position C1014T, appear not to be associated with susceptibility to lung cancer." (PMID 25031489, 2014).
pulmonary fibrosis (12 papers, 2009 to 2025). Chronic progressive interstitial lung disorder characterized by the replacement of the lung tissue by connective tissue, leading to progressive dyspnea, respiratory failure, or right heart failure. "CCL22 is a macrophage-derived chemokine previously associated with radiation pneumonitis and pulmonary fibrosis." (PMID 39808500, 2025). "At the molecular level, radioprotection appeared to be due to inhibition of CCL22, a macrophage-derived chemokine previously associated with radiation pneumonitis and pulmonary fibrosis." (PMID 39808500, 2025). "CCL22 also seems to express a role in pulmonary fibrosis, with enhanced abundance in bronchoalveolar lavage fluid and serum of patients and in mice." (PMID 39450175, 2024). "In mice, Ccl22 is produced during the pathogenesis of bleomycin-induced pulmonary fibrosis and Ccr4-/- mice are protected from pulmonary fibrosis." (PMID 39768150, 2024). "Alveolar macrophages from lung fibrosis patients spontaneously produce CCL22 and exhibit increased CD206 expression, an M2 marker." (PMID 39768150, 2024). "Conversely, CCL22 has also been reported to be elevated in bleomycin-induced pulmonary fibrosis and in idiopathic pulmonary fibrosis." (PMID 39324144, 2024). "In a rat model of radiation pneumonitis/pulmonary fibrosis, CCL22 and CCL17 were upregulated in irradiated lung tissues." (PMID 35365161, 2022). "The levels of CCL22 are also elevated in the lavage fluid obtained from patients with idiopathic pulmonary fibrosis." (PMID 26424214, 2015). "Additionally, these results also suggest the possible association between the specifically co-expressed genes such as Ccl22, Asgr2, and Slc27a3, and pulmonary fibrosis." (PMID 40269953, 2025). "CCL22 is overexpressed in a mouse model of bleomycin-induced pulmonary fibrosis." (PMID 39808500, 2025). "It has been shown that Ccl22 and Cxcr2 promote the pathogenesis of pulmonary fibrosis." (PMID 38162655, 2023). "Similarly, bronchoalveolar lavage fluid from patients with idiopathic pulmonary fibrosis exhibited elevated levels of CCL22." (PMID 35365161, 2022). "For instance, CCL22 and CCL17, secretd by M2 macrophages, can recruit CCR4+CD4+ T helper 2 cells, thereby contributing to the pathophysiology of pulmonary fibrosis." (PMID 38789926, 2024). "We examined the expression of CCR4, a specific receptor for CCL22 and CCL17, in bronchoalveolar lavage (BAL) fluid cells, as well as the levels of CCL22 and CCL17, to elucidate their pathophysiological roles in pulmonary fibrosis." (PMID 19715610, 2009). "We have previously demonstrated the selective upregulation of CCL22 and CCL17 in a rat model of radiation pneumonitis/pulmonary fibrosis." (PMID 19715610, 2009). "Thus, CCL22 and CCL17 are released by alveolar macrophages and may act on CCR4+ type-2 T helper cells and alveolar macrophages to promote pulmonary fibrosis." (PMID 35365161, 2022).
psoriasis (11 papers, 2009 to 2024). An autoimmune condition characterized by red, well-delineated plaques with silvery scales that are usually on the extensor surfaces and scalp. "The heatmap showed that C–C motif chemokine ligands (Ccl3, Ccl4, Ccl5, Ccl17, Ccl19-Ps2, and Ccl22) were expressed at higher levels in IMQ-induced psoriasis." (PMID 38566145, 2024). "CCL4L2 and CCL22 are pivotal chemokines in patients with psoriasis to stimulate the chemotactic infiltration of dendritic cells and macrophages." (PMID 34054833, 2021). "For example, intrinsic AD in contrast to extrinsic AD showed upregulation of psoriasis-typical genes (e.g., IL22, IL36G, CCL19, and CCL22) complicating discrimination of intrinsic AD and psoriasis." (PMID 31973112, 2020). "Baseline substudy serum samples from patients with psoriasis (n = 118) contained significantly (all P < .01) higher concentrations of IL-17A, IL-17F, IL-22, IL-8, CCL22/macrophage-derived chemokine (MDC), and CCL4/MIP-1β than an independent, healthy control serum cohort (n = 25)." (PMID 39114670, 2024). "Moreover, ligands for CCR4—CCL17 and CCL22, and CCR10—CCL27 have been associated with AD, psoriasis, cutaneous lymphomas, and systemic sclerosis." (PMID 37371632, 2023). "Furthermore, the TNF- α treatment exhibited enhancement effect on mRNA expression of CCL17, CCL22 in HUVECs, which was similar to psoriasis sera." (PMID 29066845, 2017). "Our data showed that serum from psoriasis patients or TNF-α promoted the protein expression of CCL17 and CCL22 in HUVECs while serum from normal in culture medium silenced the expression of these chemokines." (PMID 29066845, 2017). "However, a significant number of genes which may be induced by IL-23 or IL-22 such as GRO-1 (CXCL1), S100A7, S100A8, STAT3, IL-6, SCYA20 (CCL20), SCYA22 (macrophage-derived chemokine/CCL22), and β-defensin 2 have been identified in psoriasis microarray studies." (PMID 19884985, 2009). "Besides, IRF4+ cDC2 cluster that displays an elevated expression of CCL17, CCL22, and a population of fibroblasts that expressed CCL19 and BAFF were reported in psoriasis biopsies." (PMID 34777377, 2021). "Across five patients with psoriasis, we reported a sub-cluster of DCs (IRF4+ cDC2) that displays elevated expression of CCL17, CCL22, and IL12B, markers of cDC2s that have recently been shown to drive psoriatic inflammation in mice and humans through the recruitment of inflammatory T cells." (PMID 33053333, 2020).
autoimmune disease (8 papers, 2013 to 2026). A disorder resulting from loss of function or tissue destruction of an organ or multiple organs, arising from humoral or cellular immune responses of the individual to their own tissue constituents. "For example, MDC/CCL22-producing resident macrophages have been associated with the inflammatory profile of patients with autoimmune Sjögren’s Syndrome, an autoimmune disease affecting the secretory glands in the body." (PMID 37685890, 2023). "Interestingly, CCL22 has been previously implicated in autoimmune diseases associated with WM pathology." (PMID 25970596, 2015). "In some autoimmune diseases activation of Tregs by CCL22 has a protective effect, but contrasting results have also been reported." (PMID 32179746, 2020). "Studies have found that CCL22 is highly expressed in autoimmune diseases, such as in patients with rheumatoid arthritis, psoriatic arthritis and osteoarthritis and in patients with experimental autoimmune encephalomyelitis." (PMID 31134047, 2019). "The prominent role of Th17 cells in MS suggests further work should explore the role of B cell-produced CCL22 in Th17 development and autoimmune disease." (PMID 23505568, 2013). "After specific binding, the CCR4/CCL22 axis participates in the development of autoimmune diseases." (PMID 31134047, 2019). "Considering that tumour sites impose distinct chemokine (e.g., CCL22, CCL28) and nutrient constraints compared with inflamed autoimmune tissues, integrating these contexts could broaden the translational relevance of our model to both malignancy progression and autoimmune disease." (PMID 40960283, 2026).
eosinophilia (8 papers, 2009 to 2025). "The top proteins with the largest log2 fold change in this group included IL-19, STAT5B, CCL17, S100A12, and CCL22—inflammatory mediators known to be associated with AD inflammation and eosinophilia." (PMID 41357518, 2025). "Analyzing all the subjects from AD group (Groups 1 and 2) eosinophilia correlated positively only with CCL-22 (r = 0.36, P = .02)." (PMID 19639049, 2009). "In line with this, in a model of schistosome egg induced pulmonary granulomatous inflammation, depletion of known eosinophil and Th2 cell chemokines CCL17 and CCL22, which can be produced by DCs, led to altered granuloma structure, including a dramatic reduction in eosinophilia." (PMID 35958580, 2022). "In our study, the cytokine profile of peptide 23-immunized mice depicting elevated CCL17, CCL22, and IL-18 might have contributed to the antiviral responses rather than the induction of lung inflammation, in which no significant eosinophilia was observed." (PMID 21980478, 2011).
glioblastoma (8 papers, 2017 to 2025). The most malignant astrocytic tumor (WHO grade IV). "In glioblastoma, tumor cells can secrete chemokines such as C-C motif chemokine ligand 22 (CCL22), which binds to the C-C chemokine receptor type 4 (CCR4) receptor on the surface of Tregs, thereby recruiting Tregs and enhancing immunosuppression." (PMID 41188782, 2025). "This is important information as CCL22 may be produced by IDO+ dendritic cells in glioblastoma, which in turn may increase the generation of T regulatory cells in glioblastomas." (PMID 28481241, 2017). "Additionally, CCL22 has been shown to recruit differentiated Tregs into the glioblastoma TME." (PMID 38213329, 2023). "On the other hand, the expression of CCL17 and CCL22 is elevated in a breast cancer tumor, CCL22 expression is increased in colorectal adenocarcinomas, while CCL17 expression is increased in glioblastoma multiforme." (PMID 33182504, 2020). "In a double-blind, placebo-controlled phase 2 study, autologous DC vaccine loaded with glioblastoma-stem-cell-like lines (GSC) prolonged OS in the IDH1-wildtype TERT-mutant and B7-H4 low expression newly-diagnosed GBM patients, with increasing levels of plasma CCL22 and IFN-γ." (PMID 37444531, 2023). "While most of the analyzed chemokines (listed in Section 2) were not released by ferroptotic glioblastoma cells, we detected variations for CXCL1, CCL18, CCL20, and CCL22; however, these were not significant when comparing RSL3 to RSL3/liproxstatin-1." (PMID 41300529, 2025). "The CCR4 chemokines were not selected for further analysis as we observed low proportions of non-lymphocyte cell populations expressing the complementary chemokines CCL17 and CCL22 via scRNA-seq and observed no enrichment of CCR4+ T cells in glioblastoma." (PMID 35464424, 2022).
liver cancer (8 papers, 2018 to 2024). An epithelial or non-epithelial malignant neoplasm that arises from the liver. "Overexpression of CCL22 in human tumors was reportedly associated with increased infiltration of Tregs, along with augmented tumor growth and poor prognosis in breast, gastric, and liver cancer." (PMID 34391381, 2021). "Not only CCR4 but also its ligands CCL17 and CCL22 were found to be highly overexpressed in human and mouse liver cancers." (PMID 37081509, 2023). "Here, pre-interventional serum concentrations of IL-8 and IL-6 were significantly elevated in patients with liver cancer compared to healthy controls, while serum levels of CCL22 were unaltered between these groups." (PMID 29899223, 2018). "It has been previously reported that a TGF-β-miR-34a-CCL22 axis promotes venous metastases of HBV-positive liver cancer." (PMID 30543324, 2018). "Tumor cells release signals to recruit Treg cells to escape the immune system’s elimination, but miR-34a can inhibit CCL22, a vital molecule in the recruitment of Treg cells by liver cancer cells, and increase the infiltration of Treg cells in a mouse liver cancer model." (PMID 37465677, 2023). "However, some researchers have found that in pancreatic and liver cancer, CCL22 is produced by dendritic cells in the tumor, while the cancer cells themselves do not secrete CCL22 in vitro or in vivo." (PMID 35176085, 2022). "Given that p65 modulated miR‐23a expression, and that CCL22 was a direct target of miR‐23a, it was speculated that the p65/miR‐23a/CCL22 axis was existed in the liver cancer cells." (PMID 31769216, 2020). "In addition to CCR4, its ligands CCL17 and CCL22 found to be elevated in liver cancer, which facilitate Tregs cell infiltration to the tumors leading to the suppression of anti-cancer immunity by TGF-β1 production, and further establishment of a favorable microenvironment for tumor growth." (PMID 37081509, 2023). "Here, we aimed at evaluating circulating levels of IL-6, IL-8, and CCL22 as serum markers for patients undergoing TACE for primary and secondary liver cancer." (PMID 29899223, 2018).